LGALS3 (galectin 3)
Diseases named in the same sentence as LGALS3 in open-access papers (continued):
Sharing a sentence is not in itself a finding about the gene and the disease.
periodontitis (17 papers, 2021 to 2025). An acute or chronic inflammatory process that affects the tissues that surround and support the teeth. "However, the results of one study indicated that patients with periodontitis and with periodontitis associated with coronary heart disease had higher serum and salivary Galectin-3 levels compared with CHD patients and healthy controls." (PMID 37981665, 2023). "Periodontitis and their biomarkers galectin 3 and NLRP3 are related with halitosis in very recent literature." (PMID 38954692, 2024). "For Galectin-3, all post hoc pairwise comparisons were statistically significant with periodontitis group having the highest value followed by gingivitis group then the healthy group which shows the lowest value (p < 0.001)." (PMID 38743248, 2024). "The study showed statistical significance between different groups regarding Galectin-3 with higher values in periodontitis and the lowest values in healthy control." (PMID 38743248, 2024). "The galectin-3 and galectin-9 levels were significantly higher in the periodontitis and gingivitis groups than in the healthy group (p < 0.001)." (PMID 37809904, 2023). "This study aimed to compare the salivary galectin-3 and galectin-9 levels in periodontitis, gingivitis, and periodontally healthy patients." (PMID 37809904, 2023). "Periodontitis and ET-1 were the significant predictors of serum and salivary galectin-3 levels, respectively." (PMID 34149840, 2021). "The salivary galectin-3 and galectin-9 levels were high in patients with periodontitis and gingivitis, suggesting that they could be potential biomarkers for periodontal diseases." (PMID 37809904, 2023). "Thus, it has been shown that periodontitis is a significant predictor of serum Galectin-3 levels and nod-like receptor family pyrin domain-containing protein-3, biomarkers of endothelial dysfunction in patients with periodontitis, coronary heart disease, and type-II diabetes mellitus." (PMID 35637653, 2022). "Another article showed that patients with periodontitis and periodontitis + CHD presented significant higher serum and salivary Galectin-3 levels in comparison with CHD patients and healthy subjects." (PMID 38954692, 2024). "Recent studies regarding Galectin-3, NLRP3, and suPAR have provided clues on the synergistic effect in periodontitis evolution and inflammation." (PMID 39453923, 2024). "Recent studies have highlighted the roles of galectin-3, Nod-like receptor pyrin domain-containing protein-3 (NLRP3), and soluble urokinase-type plasminogen activator receptor (suPAR) in periodontitis progression and their interactions with CRP." (PMID 39453923, 2024). "The results showed that patients with periodontitis presented significantly more inflammatory mediators, such as TNF-α, IL-6, IL-8, ADMA, Galectin-3, in comparison with healthy subjects." (PMID 35473620, 2022). "Understanding the intricate interplay between Galectin-3, NLRP3, suPAR, CRP, and periodontitis requires further studies, which could lead to pivotal findings for elucidating disease mechanisms and identifying potential therapeutic targets." (PMID 39453923, 2024).
prediabetes (17 papers, 2016 to 2025). "The independent association between LS and galectin-3 levels in our study suggests that patients should be closely monitored for MASLD starting from the prediabetes stage and evaluated using these parameters in the early period." (PMID 40292099, 2025). "The present results on the diagnostic value of galectin-3 regarding cardiac function in euglycaemia, prediabetes and T2DM contribute to these pivotal findings." (PMID 34561496, 2021). "Already in the precursor status of prediabetes an association between galectin-3 and the systolic function was detected." (PMID 34561496, 2021). "The associations between galectin-3 level and systolic and diastolic function in prediabetes and T2DM were assessed with multiple linear regression models." (PMID 34561496, 2021). "Diastolic dysfunction (E/E′ ratio) was associated with increasing galectin-3 levels in prediabetes after adjustment for sex and age, but after additional adjustment for traditional CVRF the association was attenuated." (PMID 34561496, 2021). "Higher galectin-3 levels related to older age, female sex and higher prevalence for prediabetes, T2DM, cardiovascular risk factors and comorbidities." (PMID 34561496, 2021). "Lower galectin-3 levels were associated with euglycaemic state, whereas higher galectin-3 was related to a higher prevalence of prediabetes (increase of approximately 50% from the first to the third tertile) and T2DM (almost tripled prevalence from the first to the third tertile)." (PMID 34561496, 2021). "In our study, we aimed to evaluate the relationship between LS and galectin-3 levels in patients diagnosed with prediabetes." (PMID 40292099, 2025). "Considering the increased prevalence of MASLD in prediabetes, we recommend early assessment of LS using non-invasive methods and measurement of galectin-3 levels in these patients." (PMID 40292099, 2025). "In our study, we aimed to evaluate the relationship between liver stiffness (LS) and galectin-3 levels in patients diagnosed with prediabetes." (PMID 40292099, 2025). "In conclusion, we found that LS and galectin-3 levels were increased in patients diagnosed with prediabetes and that there was an independent relationship between LS and galectin-3 levels." (PMID 40292099, 2025). "In our study, we found that Fib-4 index, LS and galectin-3 levels were increased in patients with prediabetes." (PMID 40292099, 2025). "Considering the increased prevalence of MASLD in prediabetes, we recommend early assessment of LS and measurement of galectin-3 levels in these patients." (PMID 40292099, 2025). "Prognostic value of galectin-3 compared to NT-proBNP concerning cardiac function and mortality was assessed in individuals with euglycaemia, prediabetes and T2DM in 5 years follow-up." (PMID 34561496, 2021). "The present study provided a comprehensive analysis of the relationship between galectin-3 and the cardiac function concerning prediabetes and T2DM status compared to euglycaemic individuals in a large population-based study cohort." (PMID 34561496, 2021). "The most distinct relation between galectin-3 level given in tertiles and mortality was seen in T2DM, and in prediabetes the association was still higher compared to euglycaemia." (PMID 34561496, 2021). "The role of galectin-3 as a marker for mortality in prediabetes and T2DM was investigated with Cox regression models." (PMID 34561496, 2021). "Prior to exercise training, those with RA, compared with those with prediabetes, had similar muscle cytokine concentrations but greater plasma galectin-3 and less skeletal muscle myostatin (P <0.05 for myostatin)." (PMID 30587230, 2018). "Improved cardiorespiratory fitness (increased absolute peak maximal oxygen consumption, or VO2) correlated with reductions in galectin-3 (r = −0.57, P = 0.05 in RA; r = −0.48, P = 0.23 in prediabetes)." (PMID 30587230, 2018).
prediabetes (continued). "Additionally, studies showing the relationship between LS and galectin-3 levels in patients diagnosed with prediabetes is very scarce." (PMID 40292099, 2025). "Specifically, the authors found higher abundances of Enterobacteriaceae species (dominated by E. coli) and lower levels of host proteins that are potentially involved in Proteobacteria-specific responses in prediabetes, such as galectin-3 and proteins within the immunoglobulin super-family." (PMID 38068801, 2023). "In contrast to our hypothesis, plasma galectin-3, skeletal muscle cytokines, and muscle myostatin were unaffected by 10 weeks of high-intensity interval training in persons with RA and prediabetes." (PMID 30587230, 2018). "Although those with RA were younger than those with prediabetes, RA had greater plasma galectin-3." (PMID 30587230, 2018). "To determine whether exercise training could improve remodeling, we measured changes in inter-relationships of plasma galectin-3, skeletal muscle cytokines, and muscle myostatin in patients with RA and prediabetes before and after a high-intensity interval training (HIIT) program." (PMID 30587230, 2018). "Exercise training did not reduce mean concentration of galectin-3, muscle cytokines, or muscle myostatin in persons with either RA or prediabetes." (PMID 30587230, 2018). "The inverse relationship of improved cardiorespiratory fitness (peak VO2) with reductions in galectin-3 was similar to RA, but non-significant, in prediabetes (Fisher r-to-z P = 0.81)." (PMID 30587230, 2018). "Galectin-3 cross-sectionally was related to impaired systolic (β − 0.36, 95% CI − 0.63/− 0.09; P = 0.008) and diastolic function (β 0.014, 95% CI 0.001/0.03; P = 0.031) in T2DM and reduced systolic function in prediabetes (β − 0.34, 95% CI − 0.53/− 0.15; P = 0.00045)." (PMID 34561496, 2021). "Thus, galectin-3 may be an important biomarker in T2DM and also be useful in patients with prediabetes." (PMID 34561496, 2021).
amyotrophic lateral sclerosis (16 papers, 2012 to 2025). Amyotrophic lateral sclerosis (ALS) is a neurodegenerative disease characterized by progressive muscular paralysis reflecting degeneration of motor neurons in the primary motor cortex, corticospinal tracts, brainstem and spinal cord. "Histochemical and immunoelectron microscopy has demonstrated 5D4 positive KS modified with sialic acid and fucose in Mac2/galectin‐3‐positive activated or proliferating microglia in an Amyotrophic lateral sclerosis (ALS) mouse model." (PMID 40862528, 2025).
liver cirrhosis (16 papers, 2014 to 2025). "Liver cirrhosis increased the risk of AF (HR = 1.46; 95% CI = 1.18–1.80), likely due to cirrhotic cardiomyopathy, vasoactive intestinal peptide, and galectin-3." (PMID 34539379, 2021). "The relationship between galectin-3 and the risk of liver cirrhosis was explored in six study cohorts, all of which selected healthy volunteers as the control subjects." (PMID 34778306, 2021). "Galectin-3 in serum is increased in liver cirrhosis and is positively associated with Child-Pugh and MELD scores." (PMID 28661458, 2017). "In liver cirrhosis, hepatocyte galectin-3 levels are strongly induced, whereas in patients with cholestasis, mostly galectin-3 expression of Kupffer cells is upregulated." (PMID 38731984, 2024). "By analyzing the Co-DEGs associated with the progression and prognosis of liver cirrhosis, we identified five key genes: SOX4, LGALS3, SERPINE2, CD52, and LPXN." (PMID 39194690, 2024). "Serum galectin-3 level was significantly higher in the patients with liver cirrhosis compared to the healthy volunteers (MD = 1.83, 95% CI = 1.15–2.51, p < 0.001) with a significant heterogeneity (I2 = 98.3%, p < 0.001)." (PMID 34778306, 2021). "In liver cirrhosis patients, this distribution is changed, and galectin-3 concentrations are higher in the hepatic vein than the portal vein blood." (PMID 28661458, 2017). "Systemic levels of adiponectin, omentin, resistin, galectin-3 and IL-6 are higher in patients with liver cirrhosis, while chemerin is reduced." (PMID 28661458, 2017). "In cirrhotic liver, galectin-3 is further detected in hepatocytes, suggesting raised hepatic galectin-3 production in liver cirrhosis." (PMID 28661458, 2017). "Not only heart fibrosis but also upregulation of galectin-3 has been described in animal model for hepatic and renal fibrosis; in human liver cirrhosis; and in idiopathic lung fibrosis and chronic pancreatitis." (PMID 25960597, 2015). "Lgals‐3 encodes galectin‐3 (Gal‐3), another member of the lectin family, implicated in the development of liver cirrhosis, immunosuppression in cancer, and with a negative prognostic value in HCC." (PMID 34748271, 2022). "Clinical trials of the galectin-3 inhibitors GB1211 and Belapectin for the treatment of liver cirrhosis are currently in phase II clinical trials (ClinicalTrials.gov Identifier: NCT05009680, NCT02462967)." (PMID 39194690, 2024). "Serum galectin-3 is increased in patients with liver cirrhosis compared to the healthy controls and non-cirrhotic patients with chronic liver disease." (PMID 28661458, 2017).
preeclampsia (16 papers, 2016 to 2025). Preeclampsia is a hypertensive disorder of pregnancy that is characterized by new-onset hypertension with proteinuria presenting after 20 weeks of gestation, and depending on mild or severe forms may initially present with severe headache, visual disturbances, and hyperreflexia. "Beyond PROM, dysregulation of galectins has been implicated in other pregnancy disorders, such as preeclampsia, where placental galectin-3 levels are markedly reduced and correlate with impaired trophoblast invasion." (PMID 41329698, 2025). "Two emerging pathways, anti-angiogenic FK506-binding protein-like (FKBPL) and pro-inflammatory galectin-3 (Gal-3), have been implicated in preeclampsia and associated cardiovascular complications." (PMID 36652019, 2023). "mRNA expression of LGALS3 (galectin-3 encoding gene) was reduced in 29 women with early-onset preeclampsia, compared to 18 controls (p = 0.009)." (PMID 36311252, 2022). "The placental expressions of galectin-1 and galectin-13 were decreased in early pregnancy loss and preeclampsia, whereas the expressions of galectin-3 and galectin-9 were increased in preeclampsia." (PMID 33796532, 2021). "Additionally, galectin-3 has been linked to the regulation of angiogenesis, a process that is known to be dysregulated in preeclampsia." (PMID 39200778, 2024). "Significant correlations were observed between certain miRNAs (e.g., miR-133a, miR-195) and NT-proBNP or galectin-3 levels, particularly in the gestational hypertension subgroup." (PMID 40075783, 2025). "The identification of galectin-3 as a biomarker for preeclampsia has important implications for the development of new diagnostic and prognostic tools for this condition." (PMID 39200778, 2024). "Despite the fact that in both samples, the results were inconsistent, this review shows that galectin-3 can play a crucial role in the pathogenesis of preeclampsia, and its expression is influenced by gestational age and placental insufficiency." (PMID 39200778, 2024). "Inflammation is a key feature of preeclampsia, and galectin-3 has been shown to play a pro-inflammatory role, promoting the recruitment and activation of immune cells, such as macrophages and neutrophils." (PMID 39200778, 2024). "The included articles aimed to investigate the possible role of galectin-3 in gestational hypertensive disorders, such as preeclampsia." (PMID 39200778, 2024). "This narrative review tries to enlighten the possible correlation of galectin-3 with gestational hypertensive disorders, such as preeclampsia." (PMID 39200778, 2024). "Here, we first confirm the abnormal expression of important vascular and inflammatory proteins, FK506-binding protein-like (FKBPL) and galectin-3 (Gal-3), in human plasma and placental tissues from women with preeclampsia and normotensive controls." (PMID 36652019, 2023). "This study aimed to characterise galectin-3 in women with preeclampsia and human trophoblast stem cells (hTSCs)." (PMID 36311252, 2022). "Further studies are required to validate these findings and determine how placental galectin-3 protein differs in early-onset and late-onset preeclampsia in both phenotypes." (PMID 36311252, 2022). "Placental galectin-3 protein was significantly reduced in 43 women with early-onset preeclampsia compared to 21 controls." (PMID 36311252, 2022). "Galectin-3 protein and mRNA expression were measured in placenta of patients with early-onset preeclampsia who delivered before 34 weeks’ gestation." (PMID 36311252, 2022). "Galectin-3 was measured in placental lysates and plasma collected from patients with early-onset preeclampsia (delivered <34 weeks’ gestation) and gestation matched controls." (PMID 36311252, 2022). "As galectins can be secreted from inflamed tissues following cellular stress, future research would benefit from measuring multiple galectins with galectin-3 to understand their diverse roles in placentas complicated by preeclampsia." (PMID 36311252, 2022).